TNF (tumor necrosis factor)
Diseases named in the same sentence as TNF in open-access papers (continued):
Sharing a sentence is not in itself a finding about the gene and the disease.
gout (continued). "The levels of ox-LDL, hypersensitive C-reactive protein (hs-CRP), interleukin-1β, interleukin-6 (IL-6) and tumor necrosis factor-α (TNF-α) were measured in the plasma of 41 gout patients [28 in acute phase episode, 13 in intermittent phase (IP)], and in 40 healthy controls." (PMID 24068523, 2014). "Activated neutrophils produce a large number of proinflammatory cytokines, such as tumor necrosis factor (TNF)-α, interleukin (IL)-6, and IL-1β, all of which are involved in the pathogenesis and development of acute inflammation of gouty arthritis." (PMID 24353977, 2013). "Particularly, it is well accepted that gouty arthritis is primarily driven by TNF-α and IL-1β." (PMID 23304232, 2012). "Furthermore, we focused on the effect of Mangifera indica leaf on the induction of inflammatory cytokines TNF-α and IL-1β in gouty arthritis to investigate its anti-inflammatory mechanism." (PMID 23304232, 2012). "Injection of monosodium urate (MSU) crystals results in transient neutrophilic inflammation that resembles acute gouty arthritis in humans and induces major pro-inflammatory cytokines that are active in chronic inflammatory arthropathies, such as TNF-α and IL-1 and -6." (PMID 17612394, 2007). "In addition to glucose uptake, the hindrance of the tricarboxylic acid (TCA) cycle or the direct inhibition of immunoresponsive gene 1 may lead to a robust decrease in free radicals, M1-polarized macrophages, and IL-1β and TNF-α levels against gout." (PMID 39935474, 2025). "Therefore, we believe that KCNA5, PTGS2, and TNF may perform a key function in the treatment of gout with Bi-Qi capsules." (PMID 40430440, 2025). "IL-1β further promotes the release of other cytokines, such as tumor necrosis factor-alpha (TNF-α) and interleukin-6 (IL-6), and the recruitment of neutrophils, perpetuating the inflammatory response and causing the severe pain and swelling characteristic of gout flares." (PMID 39409183, 2024). "In particular, some cases of gouty arthritis were reported clinically, and only one experimental study reported that BV reduces levels of NF-κB nuclear translocation, leading to the suppression of proinflammatory cytokines such as TNF-α, IL-1β, and IL-6 in MSU-induced gouty mice." (PMID 34564665, 2021). "Consequently, inhibiting the formation and activation of inflammasomes and proinflammatory cytokines, such as TNF-α and IL-1β, is an important therapeutic strategy to alleviate swelling, pain, and inflammation in inflammatory diseases, including gouty arthritis." (PMID 34284768, 2021). "Therefore, the compound luteolin may treat gout and hyperuricemia through TNF, IL-17, and HIF-1 pathways." (PMID 33149752, 2020). "Therefore, the important targets for the management of inflammatory diseases, such as gouty arthritis include the reduction of swelling, pain, and inflammation by controlling the activation of inflammasomes, proinflammatory cytokines (TNF-α and IL-1β) and NF-κB." (PMID 28874151, 2017). "For example, overexpression of miR-488 and miR-920 significantly inhibits the gene and protein expression of IL-8 and TNF-α in MSU-induced THP-1 cells, thereby alleviating acute gouty arthritis." (PMID 41311848, 2025). "To explore the role of TLRs and key cytokines in gout pathogenesis, we reanalyzed a publicly available dataset, focusing on the expression of TLRs, IL-1β, IL-18, TNF-α, IL-10, and TGF-β in patients experiencing gout flare versus remission." (PMID 41583461, 2025). "In gouty arthritis, KMF restored the Th17/Treg imbalance by suppressing the expression of IL-17, tumor necrosis factor-α (TNF-α), and transforming growth factor-β1 (TGF-β1) in monosodium urate (MSU)-induced rats." (PMID 40918131, 2025). "Elevated serum levels of TNF-α, IL-6, and IL-1β are commonly observed in HUA and gout patients, reflecting inflammasome activation and immune dysregulation." (PMID 40870677, 2025).
gout (continued). "Treatment with a miR-20b inhibitor significantly increased NLRP3 protein levels and IL-1β and TNF-α secretion in MSU-stimulated THP-1 cells, indicating that miR-20b negatively regulates NLRP3 in an in vitro gouty arthritis model." (PMID 41311848, 2025). "In the gout state, aberrant FXR activation and pro-inflammatory cytokines (IL-1β, and TNF-α) suppress BA synthesis." (PMID 41255527, 2025). "The target genes of Terpine-4-ol, a main compound of ZP, were overlapped with the gouty arthritis-related genes such as NLRP3, PTGS2, CXCL8, IL6, TNF, IL1B, TLR4, and ALB." (PMID 39861092, 2024). "During gout flare-ups, the JAK2/STAT3 signaling pathway is activated, leading to increased expression of cytokines such as IL-6, IL-1β, and TNF-α in both the kidneys and joints." (PMID 39611154, 2024). "Parallel to the localized joint gout flare, our current work revealed that circulating CMs, IMs, and DCs were highly enriched in proinflammatory factors, such as NLRP3, IL-1B, and TNF, which exhibited relatively low expression in blood NCMs and other PBMCs." (PMID 38063198, 2023). "Subsequently, neutrophils extracted from patients with gouty arthritis were induced to form NETs by MSU crystals and added to the medium containing IL-1β, MCP-1, TNF and IL-6." (PMID 37810893, 2023). "MSU crystals are involved in inducing acute inflammation in gout through TLRs that stimulate the production of NLRP3 inflammasomes, interleukin-like factor and TNF-α." (PMID 38066599, 2023). "In a rat gouty arthritis model established by injecting MSU crystals, LJP-1 ameliorated the degree of ankle swelling in rats and decreased the IL-1β, IL-6, TNF-α, and cyclooxygenase-2 (COX-2) levels in the serum, eventually alleviating gouty arthritis." (PMID 37375383, 2023). "We found that dsDNA expression increased during gout remission, while IL-1β, MCP-1, TNF and IL-6 levels decreased significantly." (PMID 37810893, 2023). "This evidence suggests that circulating CMs and IMs are also the principal sources of the inflammatory response in gout flares, potentially through the TLR and TNF signaling pathways." (PMID 38063198, 2023). "During gout flare-ups, the activation of JAK2/STAT3 signaling results in an elevation of cytokine expression, including IL-6, IL-1β, and TNF-α, within the kidneys and joints." (PMID 38094893, 2023). "In our study, high levels of IL-1β, IL-6 and TNF-α were observed in LPS and MSU induced gout in THP-1 cells, which means gout model in vitro was successful." (PMID 35462936, 2022). "When the quail showed gout symptoms, the NLRP3 inflammasome was activated, and the expressions of IL-1β, TNF-α, IL-6, IL-8, and IL-18 were significantly increased." (PMID 36569836, 2022). "The levels of IL-1β, TNF-α and TGF-β1 in the serum of rats were used as indicators to evaluate the effect of MBD on gouty arthritis rats." (PMID 36589463, 2022). "Myosin IIA was activated at the Golgi membrane and transported Golgi-derived TNF-α vesicles toward the plasma membrane, promoting TNF-α secretion through curvature fusion and leading to inflammation in gout flares." (PMID 36139553, 2022). "Downregulation of miR-221-5p significantly promoted the expression of TNFα, IL8, and IL1β during acute gouty arthritis, and IL1β was proved to be targeted by miR-221-5p." (PMID 35812870, 2022). "In addition, LXA4 could significantly depress serum IL-1β and TNF-α in gouty arthritis rats." (PMID 36569930, 2022). "TNF signaling, HIF-1 signaling, and Jak-STAT signaling were predicted to be the potential pathways against gout." (PMID 36248423, 2022). "Hence, the inhibitors of TNF-α could contribute to the remission of gout flares." (PMID 36248423, 2022). "Compared with the CON group, the content of IL-8, TNF-α, IL-1β, NF-κB, UA in serum and ESR from the MOD group were increased, and IL-10 content were decreased indicating that the acute gouty arthritis model of animals was successfully built." (PMID 36090056, 2022).
gout (continued). "Consistently, two previous studies presented similar results showing that luteolin and luteolin-4′-O-glucoside, a structural analog of luteoloside, decreased serum TNF-α and IL-1β concentrations in MSU crystal-induced gouty arthritis." (PMID 34803702, 2021). "TNF-α, a pro-inflammatory cytokine produced by mononuclear cells and macrophages, is closely related to the severity of MSU-induced gout." (PMID 33959014, 2021). "As one of the proinflammatory factors, tumor necrosis factor-α (TNF-α) also plays important roles in the pathogenesis of osteoarticular inflammation, while a large amount of TNF-α is recovered in patients of gout." (PMID 34359507, 2021). "In this study, we found that IL-1β, TNF-α, and IL-6 were significantly increased in synovial tissues and serum of MSU-induced rat gout models, which is consistent with the characteristics of the GA inflammatory reaction." (PMID 32774151, 2020). "Therefore, baicalin may treat gout and hyperuricemia by regulating IL-17, TNF, and HIF-1 pathways." (PMID 33149752, 2020). "The inhibition of NLRP3 by QZTB, evidenced by the decreased mRNA and protein expressions of NLRP3 in the ankle joint, and the lower production of serum IL-1β and TNF-α level, further indicates the efficacy of QZTB on gouty arthritis in clinic." (PMID 31885675, 2019). "Inflammation in acute gout attacks is characterized by the production of various pro-inflammatory cytokines such as IL-1β, IL8, and TNF-α, and the infiltration of neutrophils." (PMID 29056937, 2017). "In summary, the concentrations of ox-LDL and pro-inflammatory cytokines IL-1β, IL-6 and TNF-α significantly increased in gout patients in our study, while TGF-β concentrations significantly decreased in gout patients relative to controls." (PMID 24068523, 2014). "Data from our study showed that rat with gouty arthritis induced by MSU crystal demonstrated an elevation in ankle swelling, synovial TNF-α, IL-1β mRNA, and protein levels." (PMID 23304232, 2012). "The analysis results indicate that FGF-21, MMP-1, G-CSF, and IFN-γ are involved in the pathogenesis of gout, and gout may influence the expression of CXCL1, IL-1Ra, and TNF-α." (PMID 40388724, 2025). "The pathophysiological events in gout involve the phagocytosis of urate crystals by synoviocytes, which then secrete inflammatory mediators, such as interleukin-1 (IL-1), leukotriene B4 (LTB4), prostaglandins, and tumor necrosis factor-alpha (TNF-α)." (PMID 39861750, 2025). "The systemic immune and inflammatory responses of the body gradually decrease during the evolution of gout from the acute phase to the remission phase, though the KCNA5 level in B cells and neutrophil cells was raised, and PTGS2 and TNF in B cells, macrophages, and monocytes were decreased." (PMID 40430440, 2025). "Then, we compared cytokine levels, including IFN-γ, TNF-α, IL-2, IL-4, IL-6, IL-10 and IL-17 among gout with tophus, gout without tophus and HCs." (PMID 38240927, 2024). "Another study indicated that oxidative stress and inflammatory markers including tumor necrosis factor, CRP, interleukin (IL) 1β, IL-6 may affect the development and clinical manifestations of gout based on hierarchical cluster analysis." (PMID 38678252, 2024). "Additionally, gout patients had significantly higher cytokines levels (including IL-2, IL-4, IL-6, IL-10, IL-17, IFN-γ, and TNF-α) than HCs; IL-2 levels were positively correlated with Treg cells and negatively correlated with ESR." (PMID 38240927, 2024). "In addition, we divided the onset of gouty arthritis into acute and remission stages and then assessed the expression of serum dsDNA, IL-1β, MCP-1, TNF and IL-6." (PMID 37810893, 2023). "In our study, injection of MSU crystals and feeding with HFD caused a decrease in the relative abundance of Bacteroides, which was significantly negatively correlated with the levels of UA, IL-1β, IL-6, TNF-α, MPO activity, and purine and pyrimidine metabolisms in mice with gout." (PMID 35145506, 2022).
gout (continued). "Subsequently, molecular docking technology was performed to forecast the binding form and the affinity between the key ingredients of WSP and the vital proteins such as p65, NLRP3, IL-1β, TNF-α, and p38 of TNF signaling, which were the crucial targets closely related to gout disease." (PMID 36248423, 2022). "Considering the important effect of pro-inflammatory cytokines on the development of acute gouty arthritis, we explored whether GPS could inhibit the release of IL-1β, IL-6, IL-18, and TNF-α." (PMID 34586567, 2022). "In this study, similar results were revealed showing the decreased relative abundance of Lachnospiraceae and the significantly negative correlation between the relative abundance of Lachnospiraceae and the levels of UA, IL-1β, IL-6, TNF-α, MPO activity, and purine metabolism in mice with gout." (PMID 35145506, 2022). "These anti-inflammatory fractions treat gouty arthritis by inhibiting the release of the inflammatory factors including prostaglandin E2 (PGE2) and TNF-α, which may relieve the symptoms of redness, fever and severe pain that occur during gout attacks." (PMID 36339628, 2022). "The HR for non-vertebral fractures and hip fractures in gout were consistently lower versus RA after stratifying by age, sex, 365-day cumulative dose of steroids, and absence of TNF inhibitor use." (PMID 34682784, 2021). "The expression of IL-1β and TNF-α in the joint synovial fluid of MSU-induced GA rats in the model group was significantly increased, suggesting that inflammatory factors such as IL-1β and TNF-α play an important role in acute episodes of gout." (PMID 34721647, 2021). "The core targets of plantain for treating gout are MAPK1, RELA, TNF, NFKBIA, and IFNG, and the key pathways are pathways in cancer, hypoxia-inducible factor-1 (HIF-1) signaling pathway, interleukin (IL)-17 signaling pathway, Chagas disease (American trypanosomiasis), and relaxin signaling pathway." (PMID 33149752, 2020). "In addition, JGT efficiently downregulated MSU crystal-induced swelling and pain and contrasted inflammation by suppressing pro-inflammatory cytokines (IL-1β, TNF-α, and IL-6) and MPO activity in a gouty arthritis mouse model." (PMID 33371241, 2020). "Here, we show that caspase-11−/− mice and their derived macrophages produce significantly reduced levels of gout-specific cytokines including IL-1β, TNFα, IL-6, and KC, while others like IFNγ and IL-12p70 are not altered." (PMID 31803174, 2019). "Therefore, synovial fibroblasts from gout patients with gouty arthritis were separated and treated with MSU or TNFα/IL-lβ." (PMID 30863362, 2019). "The potential anti-gouty arthritis effect of QZTB may be attributed to the inhibition of NLRP3 inflammasome and downstream proinflammatory cytokines (IL-1β and TNF-α) levels." (PMID 31885675, 2019). "Several studies have focused on the relationship between gout and candidate inflammatory genes including IL-1β, IL-6, IL-8, IL-18, and TNF-α, however, the disease pathogenesis is still not fully understood." (PMID 26890073, 2016). "IL-6, IL-8 or TNFα released by PBMCs was not significantly different between gout patients and controls for any of the stimuli, single or in combination." (PMID 22762240, 2012). "Anti-TNF agents, a cytokine that plays some role in the disease, have been used in few case reports, although experimental studies in rats with gout have not shown any inflammation inhibition of the acute response in this disease." (PMID 23304159, 2012). "Furthermore, our in vitro experiments showed that MSU crystals induced IL-1, IL-6, TNF-α and RANKL, and all were found to be highly expressed in the SFMCs of patients with gouty arthritis." (PMID 21992185, 2011). "Thus, we propose that pro-resorptive cytokines, such as IL-1, IL-6, TNF-α and RANKL, contribute to osteoclastic bone resorption in patients with chronic gout." (PMID 21992185, 2011). "TNF-α, IL-6 and PGE2 all have important roles in inflammatory arthropathies, including gout." (PMID 17612394, 2007).
gout (continued). "During the evolution from the acute phase to the remission phase of gout, KCNA5 in B cells and neutrophil cells was raised significantly, PTGS2 in B cells, macrophages, and monocytes was decreased significantly, and TNF in B cells and monocytes was also decreased significantly." (PMID 40430440, 2025). "Furthermore, in the monosodium urate (MSU)-induced gout rat model, DTX effectively suppresses pro-inflammatory cytokines, including tumor necrosis factor-α (TNF-α), interleukin (IL)-1β, and IL-6 secretion, mitigating inflammatory damage and exhibiting anti-inflammatory properties." (PMID 39170709, 2024). "Furthermore, there were no statistical differences of tear IL‐1β and TNF‐α levels between asymptomatic hyperuricemia group and gout group, suggesting that ocular inflammation has been overexpressed during the asymptomatic hyperuricemia period." (PMID 36988248, 2023). "Therefore, we speculate that the pathogenesis of gout involves hyperuricemia leading to precipitation of monosodium urate in joints, which triggers ALPK1 to activate proinflammatory cytokine (such as TNF-α) secretion." (PMID 36139553, 2022). "Therefore, dapansutrile may reduce the chemotaxis and activation of inflammatory cells for the treatment of gouty arthritis by blocking the activation of IL1B, CXCL8, and TNF." (PMID 36105284, 2022). "However, in a gouty arthritis animal model, SMWE more efficiently downregulated MSU-crystal-induced swelling and pain, and it exerted anti-inflammatory effects by suppressing proinflammatory cytokines (IL-1β, TNF-α, and IL-6) and MPO activity." (PMID 33535406, 2021). "Synthesized the results of IL-1β and TNF-α changing tendency, it is indicated that knock out miR-146a discharged the repression of TRAK6 and IRAK1 function to accelerate the production pro-inflammatory cytokines and to exacerbate the MSU-induced gouty arthritis." (PMID 29544526, 2018). "Collectively, our results suggest that the inflammatory and gouty arthritis inhibitory effects of MPE primarily occur via the down-regulation of edema, pain and inflammation through the control of inflammasomes, proinflammatory cytokines (TNF-α and IL-1β), and NF-κB." (PMID 28874151, 2017). "However, in patients with gout, MSU crystals also mediate local and systemic inflammatory processes which can induce many inflammatory cytokines, including tumor necrosis factor α (TNF-α), interleukin-1β (IL-1β), interleukin-6, and interleukin-8." (PMID 25250773, 2014). "The protein concentrations of inflammatory cytokines (IL-1β, TNF-α, and IL-6) significantly increased after ATG7 overexpression in MSU-stimulated THP-1 macrophages, suggesting that ATG7 may be involved in the mechanism of gout recurrence by promoting the release of inflammatory cytokines." (PMID 41221017, 2025). "Thus, diminishing the production of IL-1β or TNF-α in macrophages by inhibiting the M1 polarization and/or NLRP3 inflammasome activation via the NF-κB signal pathway could be an effective strategy to treat gouty arthritis." (PMID 33505510, 2021). "Therefore, baicalein may regulate TNF, HIF-1, and IL-17 pathways to treat gout and hyperuricemia." (PMID 33149752, 2020). "The current study identified that the use of ALP or ZUR alone failed to reduce levels of IL-1β and TNF-α in hyperuricemic mice, suggesting that the co-administration of ALP and ZUR exerted their anti-inflammatory effect to prevent development of gout from HU." (PMID 32041665, 2020). "MSU crystals alone failed to induce IL-1β, IL-6 or TNFα in both patients and control groups, but a stronger synergy between MSU/Pam3Cys and MSU/C18:0 for the induction of IL-1β was found in patients with gout compared to healthy controls." (PMID 22762240, 2012). "Extracellular TNF-α secretion was significantly reduced by the knockdown assays of endogenous ALPK1 and myosin IIA but not IL-1β thus IL-1β was not followed through into the human assays of gout patients." (PMID 27169898, 2016).